PADI4 (peptidyl arginine deiminase 4)
Diseases named in the same sentence as PADI4 in open-access papers (continued):
Sharing a sentence is not in itself a finding about the gene and the disease.
COVID-19 (35 papers, 2020 to 2025). A disease caused by infection with severe acute respiratory syndrome coronavirus 2. "For this reason, we length of stay performed the first candidate gene study evaluating the association of SNPs in PADI2 and PADI4 with inflammation markers, severity, and death by COVID-19." (PMID 38524554, 2024). "The main findings in our study were that: 1) SNPs rs1005753 of PADI2 and rs874881, rs11203367, and rs11203366 of the PADI4 gene are associated with susceptibility to severe COVID-19 and death." (PMID 38524554, 2024). "Our results suggest that the haplotypic combination of GTACC and some individual genotypes of PADI2 and PADI4 contribute to the subjects' susceptibility for severity and death by COVID-19." (PMID 38524554, 2024). "Carriers of the rs1005753 G/G genotype in the PADI2 gene presented susceptibility for severe COVID-19, while the heterozygous carriers in rs11203366, rs11203367, and rs874881 of the PADI4 gene showed risk of death." (PMID 38524554, 2024). "SNPs in the PADI2 and PADI4 genes associated with susceptibility to severe COVID-19 and death showed a more robust association if combined as haplotypes." (PMID 38524554, 2024). "In this study, PADI4 SNPs were associated with a higher probability of death by COVID-19, and particularly, the SNP rs11203366 was associated with D-dimer levels ≥1.25 μg/mL, which are a marker of severe infection." (PMID 38524554, 2024). "However, our results provide some perspectives on the influence of PADI2 and PADI4 gene variants on clinical and biochemical COVID-19 outcomes." (PMID 38524554, 2024). "Therefore, this study aims to analyze the individual association of SNPs and haplotypic combination in PADI2 and PADI4 with inflammation markers, severity, and death by COVID-19 in a Mexican population." (PMID 38524554, 2024). "In conclusion, individual SNPs in PADI2 and PADI4 were related to COVID-19 severity and death risk." (PMID 38524554, 2024). "The association of single SNPs and PADI2 and PADI4 haplotypes with abnormal markers of inflammation, COVID-19 severity and death might be explained by the higher expression and activity of PAD2 and PAD4 enzymes in monocytes and neutrophils." (PMID 38524554, 2024). "However, the haplotypic combination GTACC between SNPs of PADI2 [rs1005753, rs2235926] and PADI4 [rs11203366, rs11203367 and rs874881] was associated with susceptibility for severe COVID-19 (OR = 1.59, p = 0.007), as well as with susceptibility to present a PLR index ≥303 (OR = 1.93, p < 0.001)." (PMID 38524554, 2024). "In said study, they found that alarmins S100A/8/9/12 and NETs-involved PADI4 exhibited heightened expressions of granulocytes from severe COVID-19 patients." (PMID 36159873, 2022). "As reported with tobacco smoking and air pollutants, COVID-19 can act on cells in mucosal sites (mouth, lung and gut) to promote the induction of PADI-4 and in turn to the formation of citrullinated histones." (PMID 35434592, 2022). "Peptidyl arginine deiminase 4 (PAD4) is up-regulated in COVID-19 in the lung and is essential in NETosis." (PMID 36268783, 2022). "The level of three autoantigens, MPO, PRTN3, and PADI4, were higher in the blood of severe compared to mild COVID-19." (PMID 34276672, 2021). "Similarly, SNPs in PADI2 are related to the level of antibodies against citrullinated protein antigens (ACPAs), and the expression of PADI4 (mRNA) is higher in lung biopsies and leukocytes of subjects with severe COVID-19." (PMID 38524554, 2024). "Also, PADI4 mRNA levels are upregulated in leukocytes from subjects with severe COVID-19 compared to moderate COVID-19 and healthy controls." (PMID 38524554, 2024). "•The combination of PADI2 and PADI4 SNPs exhibits a synergistic role in the COVID-19 severity." (PMID 38524554, 2024).
COVID-19 (continued). "Our results also suggest that SNPs in PADI2 and PADI4 play a synergistic role as modifiers of enzymes expression or activity, contributing to the clinical manifestation and outcomes of COVID-19 due to its role in NETosis, cytokine citrullination, platelet activation, and thrombosis." (PMID 38524554, 2024). "Additionally, scRNA-seq profile for PADI4 linked to “suicidal NETosis” shows low (1.4%) number of neutrophils expressing PADI4 > 2X fold in COVID-19-ARDS neutrophils." (PMID 35379853, 2022). "These cells had a significantly high level of MPO, PRTN3, and PADI4 indicating that they could be a major source of the observed increase in blood level of these autoantigens during severe COVID-19." (PMID 34276672, 2021). "Meanwhile, CXCL8, S100A8, S100A9, S100A12, FCGR1A, PADI4, and BCL2A1 showed significant increases in severe COVID-19 when compared with mild COVID-19 (p <0.05)." (PMID 36159873, 2022). "In whole blood study, seven autoantigens were upregulated in blood of severe COVID-19 patients (MPO, PRTN3, PADI4, IFIH1, TRIM21, PTPRN2, and TSHR), while four autoantigens (MPO, PRTN3, IFIH1, and PADI4) were increased in blood of mild patients." (PMID 34276672, 2021). "Comparison of COVID-19 blood transcriptomic with IAV and RSV revealed that MPO, PRTN3, and PADI4 were selectively upregulated in coronavirus infections, SARS-CoV-1 and SARS-CoV-2, while TSHR and PTPRN2 autoantigens were distinctive to SARS-CoV-2 infection." (PMID 34276672, 2021). "However, genes related to distinct mechanisms of NET induction were differentially expressed in the COVID-19(+) TV and COVID-19(-) PU control groups, with COVID-19(+) TV samples expressing PADI2 versus PADI4 expression in COVID-19(-) PU controls." (PMID 37026002, 2023). "In parallel, only COVID-19 samples from moderate and severe cases, but not mild cases, were activated in vitro NETs, as determined by supernatant dsDNA, Peptidyl Arginine Deiminase 4, and nuclear morphology." (PMID 35406667, 2022). "For instance, IL1B, NFKB1, NLRP3, PYCARD, and CASP1 are listed in the COVID-19 Disease Map, while there are molecules absent from it, including CCL3, 3L1, 4L2, CXCL1, 2, 3, 5, 16, TNFAIP6, C15orf48, TMEM176A/B, NFE2, PADI4, RAB20, ETS2, PHLDA2, FOLR3, and HP." (PMID 37719701, 2023). "This gains relevance when neutrophils are PADI4-negative, as seen in 98.6% of neutrophils in the COVID-19-ARDS RNA-seq files, hence non-responders to PADI4-inhibitors of NET-formation." (PMID 35379853, 2022).
lupus (34 papers, 2012 to 2026). "In both acute kidney injury and lupus mouse models, renal neutrophil infiltration and NETs production were markedly reduced, and renal function was significantly improved in PADI4 knockout mice." (PMID 41208960, 2025). "PADI4 polymorphisms also confer susceptibility to SLE and lupus nephritis (LN)." (PMID 37020554, 2023). "We studied IMQ-induced lupus model mice in Padi4 KO background to explore the pathological roles of PAD4 in lupus nephritis." (PMID 32655553, 2020). "Because PAD4 is required for NETosis, the amelioration of lupus-like phenotypes in Padi4 KO mice can be partially explained by the lack of NETosis." (PMID 32655553, 2020). "As NET formation was clearly suppressed in these Padi4-deficient mice, the lack of NETs was thought to be one of the reasons for the ameliorated lupus phenotype." (PMID 36319843, 2022). "An imiquimod (IMQ)-induced lupus model was analyzed in wild-type (WT) and Padi4-knockout (KO) mice." (PMID 32655553, 2020). "In TLR7-induced lupus, PADI2 and PADI4 promote the induction of TLR7 in lupus through innate and adaptive immunity." (PMID 37020554, 2023). "Taken together with earlier work, these findings add additional evidence that challenges the concept that neutrophils and NETs, to the degree that NET generation and neutrophil effector function relies on PADI4, ELANE, or CYBB, critically drives lupus." (PMID 32243431, 2020). "First, we compared the lupus-like phenotypes induced by topical treatment of IMQ between WT and Padi4 KO mice." (PMID 32655553, 2020). "Although PADI4 has not been identified as a GWAS risk gene for SLE, PADI4 gene polymorphisms were reported to be associated with lupus nephritis." (PMID 32655553, 2020). "Taken together, in Padi4 KO-IMQ mice, lupus-like organ damage was ameliorated compared with WT-IMQ mice." (PMID 32655553, 2020). "Furthermore, myeloperoxidase and PADI4 deletion did not inhibit induced lupus." (PMID 32243431, 2020). "Our work adds ELANE to the list of CYBB and PADI4 as proteins that are required for NET formation, yet are not needed for lupus." (PMID 32243431, 2020).
atherosclerosis (27 papers, 2018 to 2026). A disease characterized by the build-up of fatty material and calcium deposition in the arterial wall resulting in partial or complete occlusion of the arterial lumen. "Studies have shown that the accumulation of PADI4-mediated NETosis at the site of intimal injury destroys the integrity of the vascular intima and promotes the occurrence of atherosclerosis, which is associated with coronary artery disease (CAD)." (PMID 37020554, 2023). "In disease contexts, such as autoimmunity, cancer, atherosclerosis and fibrosis, where PADI4 expression or activity are aberrantly high, a potent and selective inhibitor, which is specific for the active form, is likely to be highly advantageous." (PMID 39528459, 2024). "For superficial plaque erosion in atherosclerosis, collagen IV-targeted nanoparticles were developed to deliver the PADI4 inhibitor GSK484 selectively to regions of endothelial cell injury and basement membrane exposure." (PMID 38612791, 2024). "In atherosclerosis and thrombosis, PADI4 can lead to an inflammatory response and thrombosis by promoting NETosis." (PMID 37020554, 2023). "Intimal damage from atherosclerosis leads to thrombus formation, which is promoted by NETosis that is mediated by the upregulation of PADI4." (PMID 37020554, 2023). "The specific deletion of peptidyl arginine deiminase-4 (PAD4) reduces the formation of NETs and significantly alleviates atherosclerosis, complications, and inflammation caused by macrophages." (PMID 34926629, 2021). "As NETs directly promote atherosclerosis, the use of specific PADI4-inhibitors, in order to suppress the PADI4-dependent NET formation, might have therapeutic benefits in atherosclerosis and cardiovascular complications." (PMID 33925019, 2021). "Deleting peptidyl arginine deiminase-4 (PAD4) specifically decreases NETs production and greatly reduces macrophage-induced inflammation, and atherosclerosis." (PMID 38328614, 2024). "Peptidylarginine deiminase IV (PADI4, PAD4) deregulation promotes the development of autoimmunity, cancer, atherosclerosis and age-related tissue fibrosis." (PMID 39528459, 2024). "The specific knockout of PADI4 in mice, which is known to largely prevent NET formation, showed marked disease abrogation in atherosclerosis, venous thrombosis, heparin-induced thrombocytopenia, superficial plaque erosion in ACS, myocardial IR, and ischemic stroke." (PMID 38612791, 2024).
Autoimmunity (26 papers, 2015 to 2026). The occurrence of an immune reaction against the organism's own cells or tissues. "Importantly, they provide a platform for the development of cell modulatory and therapeutic agents applicable to the broad-ranging contexts of PADI4 deregulation, which include autoimmunity, cancer and age-related pathologies." (PMID 39528459, 2024).
colitis (23 papers, 2020 to 2026). Inflammation of the colon. "Some pre-clinical results showed that peptidyl arginine deiminase 4 (PAD4) inhibitors and DNase I can relieve experimental colitis through inhibiting NET formation or increasing NET degradation." (PMID 39328405, 2024).
diabetes (21 papers, 2016 to 2026). "Diabetes can trigger neutrophils to undergo histone citrullination by protein arginine deiminase 4 (encoded by Padi4 in mice) and release neutrophil extracellular traps (NETs)." (PMID 36594092, 2023). "In diabetes, increased activity of enzymes such as peptidyl arginine deiminase 4 (PAD4), neutrophil elastase, and protein kinase C leads to excessive NET formation." (PMID 41328337, 2026). "Macroscopic analysis and histological evaluation revealed a substantial improvement in wound closure in Padi4-/- mice with diabetes (inhibition of NETosis) when compared with the delayed wound closure observed in wild-type mice with diabetes." (PMID 38993565, 2024).
Stroke (19 papers, 2011 to 2025). Sudden impairment of blood flow to a part of the brain due to occlusion or rupture of an artery to the brain. "Stroke Homing peptide (SHp)-guided deoxyribonuclease 1 (DNase1) and inhibition of myeloperoxidase (MPO) or peptidyl arginine deiminase-4 (PAD4) can reduce chemotherapy-induced mechanical hyperalgesia and prevent the development of CIPN in mice model." (PMID 39202733, 2024). "Elevated peptidyl arginine deiminase 4 (PAD4) levels have been detected in blood samples collected during carotid artery stenting, suggesting the involvement of NETs in the pathogenesis of atherothrombotic stroke." (PMID 38187160, 2023).
thrombosis (19 papers, 2012 to 2024). "In heparin-induced thrombocytopenia (HIT) mice, PADI4 enhances neutrophil-endothelial cell adhesion and neutrophil clot infiltration through NETosis, thereby promoting the formation and progression of venous thrombosis." (PMID 37020554, 2023). "NETs were also identified as major drivers of heparin-induced thrombocytopenia/thrombosis (HIT), where IgG-heparin/platelet factor 4 complexes interact with FcγRIIa on neutrophils to trigger the formation of NET-rich thrombi, which could be blocked with PADI4 inhibitors experimentally." (PMID 38612791, 2024).
lung carcinoma (16 papers, 2009 to 2025). "The levels of citrullinated antithrombin were significantly associated with PADI4 levels in blood of patients with hepatocellular carcinomas, lung cancer, ovarian cancer, endometrial carcinomas, and thyroid adenomas." (PMID 20222985, 2010). "cAT levels associated significantly with PADI4 levels in patients with hepatocellular carcinomas, lung cancer, ovarian cancer, endometrial carcinomas and thyroid adenomas (p < 0.01)." (PMID 19183436, 2009). "We observed more citrullinated peptides in the MDA-MB-231 LM3 model compared to the PC9 lung cancer model, potentially due to higher Padi4 levels in MDA-MB-231 LM3 cells." (PMID 40751052, 2025). "PADI4 have been reported play an important role in the pathogenesis of lung cancer by mediating EMT." (PMID 35045833, 2022). "PADI4 also plays an important role in tumorigenesis and pathogenesis in lung cancer, colorectal cancer, oesophageal cancer and ovarian carcinoma." (PMID 35045833, 2022). "We and others have found that PADI4 is overexpressed in many cancers, including ovarian cancer, colorectal cancer, lung cancer, cervical squamous cell carcinoma and thyroid carcinoma." (PMID 35045833, 2022). "Notably, in the human cancer cell line atlas, more lung cancer cell lines showed high Padi4 expression compared to other solid tumors, which is consistent with our CitH3 results." (PMID 36973439, 2023). "Notably, both Padi4 and the nuclear expulsion signature showed worse overall survival specific for patients with lung cancer." (PMID 36973439, 2023). "This indicates that free DNA is the most useful diagnostic marker for lung cancer and that the combination of DNA with either PPBP and PADI4 or COX2 could improve diagnostic accuracy, especially of early stage tumors." (PMID 23468981, 2013). "Finally, BBR could prevent lung cancer by modulating the peptidylarginine deiminase 4 (PADI4)-related macrophage inflammatory responses by up-regulating CD86 and decreasing CD163 and CD206 in the PADI4 overexpressed macrophages." (PMID 36561763, 2022). "As PADI4 is a positive regulator of EMT, we further clarified the role of Gimap5 in inhibiting lung cancer via EMT downregulation." (PMID 34604035, 2021). "Its downstream signaling has been studied in the progression of a variety of human cancers, but there is a lack of studies showing the efficacy of PADI4 in lung cancer." (PMID 36233212, 2022). "Using nontoxic doses of the remaining inhibitors, KDM6B and PADI4 were identified as potential targets affecting the invasion and migration of metastatic lung cancer cell lines." (PMID 36233212, 2022). "Combined with PADI4 expression, PPBP expression may be considered a non-invasive multi-marker approach offering diagnostic and clinical value in patients with suspected lung cancer." (PMID 38612651, 2024). "Therefore, we believed that Gimap5 might play a role in the degradation of M6P modified ligands (i.e., PADI4) via M6PR, thereby inhibiting the growth of lung cancer." (PMID 34604035, 2021).